POT1 (protection of telomeres 1)
Diseases named in the same sentence as POT1 in open-access papers (continued):
Sharing a sentence is not in itself a finding about the gene and the disease.
melanoma (continued). "Deleterious POT1 mutations are present in approximately 3% of all tumors, with a higher prevalence in angiosarcomas, non-small-cell lung cancers, and cutaneous squamous cell carcinomas and melanomas." (PMID 32987645, 2020). "While one germline mutation in POT1 has already been reported in a melanoma-prone family with prevalence of thyroid cancers, we report the first of such mutations in a family affected solely by NMTCs, thus expanding current knowledge on shelterin complex-associated cancers." (PMID 32492864, 2020). "In a study of CDKN2A/CDK4 wild-type melanoma-prone families recruited from Australia, UK and the Netherlands, four pedigrees were found (3.8%, n = 4/105) in which melanoma co-segregated with POT1 germline variants (p.Tyr89Cys, p.Gln94Glu, p.Arg273Leu, and c.1687-1G > A)." (PMID 32987645, 2020). "In addition, germinal mutations in the Pot1 shelterin gene, which lead to longer telomeres than normal, have been also associated to various types of familial cancer, such as melanoma, Li-fraumeni like, and glioma." (PMID 31624261, 2019). "Recent studies reported germline variants in POT1 in melanoma families." (PMID 29523635, 2018). "Here we present for the first time data of POT1 variants in high-risk melanoma patients in Austria." (PMID 29523635, 2018). "So, in conclusion, melanoma associated POT1 germline variants seem to be rare." (PMID 29523635, 2018). "Additionally, high penetrance melanoma mutations have been reported in genes encoding components of the Shelterin complex (POT1), which is crucial for the maintenance and signaling function of telomeres: POT1 mutations resulted in longer telomeres." (PMID 25231748, 2014). "Furthermore, hereditary melanoma has been associated with germline mutations in high-risk melanoma susceptibility genes (CDKN2A, CDK4, TERT, POT1), polymorphisms in intermediate-risk melanoma susceptibility genes (BAP1, ACD, TERF2IP, MC1R and MITF), and germline missense substitutions in MITF." (PMID 32276436, 2020). "In conclusion, melanoma driving POT1 germline variants might be rare." (PMID 29523635, 2018). "Additionally, DNA methylation levels at the promoter regions of BAP1, MITF, and PALB2 genes were statistically associated with the number of melanomas presented by the individual and a hypermethylation of POT1 promoter was associated with Breslow thickness of the tumors." (PMID 26106605, 2015). "Multigene panel testing, including genes like CDKN2A, CDK4, BAP1, POT1, ACD, and TERF2IP, enhances the detection of hereditary melanoma risk." (PMID 39941357, 2025). "POT1 PVs were rare in the studied Swedish familial melanoma cases, implying limited contribution to hereditary melanoma in this population." (PMID 40851494, 2025). "With respect to genetic testing in clinical practice, in England, POT1 has recently been included in the familial melanoma panel." (PMID 40350252, 2025). "POT1 testing should be considered in families with multiple melanomas, early onset and spitzoid histopathology, and co-occurring with other syndromic tumors." (PMID 40851494, 2025). "Among the 161 CDKN2A/CDK4/BAP1-negative melanoma families included in this cohort, only one likely PV in POT1 (c.676C > A, p.His226Asn) was identified (0.6%)." (PMID 40851494, 2025). "Only one family with a likely PV was identified; hence, the frequency of POT1 PVs in this familial melanoma cohort was 0.6%." (PMID 40851494, 2025). "Other high- and moderate-penetrance genes—such as BAP1, POT1, BRCA2, and TERT—were also included, reflecting an expanded institutional approach to hereditary melanoma risk assessment." (PMID 40863406, 2025). "A recent international publication suggested guidelines for POT1 tumour surveillance relating to melanoma, AS, chronic lymphocytic leukaemia (CLL) and glioma." (PMID 40350252, 2025). "The targeted custom panel was used to examine six hereditary melanoma susceptibility genes (CDKN2A, MITF, MC1R, CDK4, POT1, and BAP1)." (PMID 39156708, 2024).
melanoma (continued). "The pipeline identified variation in known germline melanoma genes POT1, MITF and BAP1 in 4 out of 13 families (31%)." (PMID 38866901, 2024). "In the case of sporadic melanomas, comprising more than 90% of all melanomas, several susceptibility loci acting as moderate (BAP1, TERT, POT1, ACD, TERF2IP and MITF) or low penetration genes have been identified." (PMID 36765773, 2023). "We sequenced all coding exons of the POT1 gene in 2928 European-descent melanoma cases and 3298 controls, identifying 43 protein-changing genetic variants." (PMID 36539277, 2023). "Pathogenic germline variants in the protection of telomeres 1 gene (POT1) have been associated with predisposition to a range of tumour types, including melanoma, glioma, leukaemia and cardiac angiosarcoma." (PMID 36539277, 2023). "In familial melanoma patients and in one AML patient with germline POT1 variants telomere length was reported to be increased, whereas in CLL cases telomere length was normal." (PMID 36467798, 2022). "Mutations of the CDKN2A carry a high risk of melanoma, together with CDK4, TERT, and POT1 gene mutations." (PMID 35465855, 2022). "Genetic predisposition accounts for nearly 10% of all melanoma cases and has been associated with a dozen moderate- to high-penetrance genes, including CDKN2A, CDK4, POT1 and BAP1." (PMID 35085295, 2022). "These methods have been applied recently to discover melanoma predisposition genes such as MITF, TERT and POT1." (PMID 35085295, 2022). "Telomere maintenance genes such as TERT, ACD, POT1 and TERF2IP were associated to melanoma predisposition previously." (PMID 35085295, 2022). "We first looked at an extended list of high-risk genes predisposing to melanoma (ACD, CDKN2A, CDK4, POT1, TERF2IP, and TERT) or RCC (CDKN2B, FH, FLCN, MET, PBRM1, PTEN, SDHs, TSCs, and VHL) or both (BAP1 and MITF)." (PMID 34067022, 2021). "In 2015, a revision of the prevalence of mutations in susceptibility CMM genes reported that, in 2511 melanoma-prone pedigrees, the mutation prevalence was about 20% for CDKN2A, 0.7% for CDK4, 1% for BAP1, and 0.5% for POT1." (PMID 33322357, 2020). "Numerous genes have been associated with melanoma: beyond CDKN2A and CDK4, primarily included as high-risk genes for familial melanoma, BAP1, POT1, and MITF were recently also identified as potential high-risk melanoma susceptibility genes." (PMID 33322357, 2020). "The overall contribution of recently identified CM predisposition genes (ACD, BAP1, POT1, MITF, and TERF2IP) to melanoma’s missing heritability is estimated to be about 2%." (PMID 32325837, 2020). "A total of 9 patients (3.4%) carried mutations in high-to-moderate melanoma risk genes (CDKN2A, POT1, ACD) and 22 (8.3%) patients in other cancer syndrome genes (NBN, BRCA1/2, CHEK2, ATM, WRN, RB1)." (PMID 33050356, 2020). "Recent studies have led to the identification of new genes involved in CMM susceptibility: beyond CDKN2A and CDK4, BAP1, POT1, and MITF were recently identified as potential high-risk melanoma susceptibility genes." (PMID 33322357, 2020). "Other studies reported that BRCA-associated protein 1 (BAP1) and protection-of-telomeres-1 (POT1) mutations, as well as multiple MC1R variants are also associated with MPM and familial melanomas." (PMID 31382929, 2019). "The melanoma predisposition due to a single gene knockout is comparable to deleterious germline variants in a number of genes such as CDKN2A and POT1 that have been shown to underlie familial melanoma cases in human patients." (PMID 28806732, 2017). "The identification of POT1 and TERT germline mutations highlights the importance of telomere integrity in melanoma biology." (PMID 26433962, 2016). "Germline CDKN2A mutations occur in 40 % of 3-or-more case melanoma families while mutations of CDK4, BAP1, and genes involved in telomere function (ACD, TERF2IP,POT1), have also been implicated in melanomagenesis." (PMID 26433962, 2016).
melanoma (continued). "More recently, rare germline mutations in the protection of telomeres 1 gene (POT1) were found in families with early onset and multiple primary melanomas." (PMID 26433962, 2016). "A rare mutation (p.Ser270Asn) with founder effect in the protection of telomeres 1 (POT1) gene has been identified in melanoma-prone families." (PMID 26322273, 2015). "Germline mutations in additional genes were recently associated with melanoma occurrence: MITF, BAP1, TERT promoter, POT1, and MGMT." (PMID 26106605, 2015). "Similarly to variants in POT1, alterations in ACD and TERF2IP increase the risk of multiple primary melanomas, which are typically diagnosed at a young age, with incidence peaking in the second decade of life." (PMID 40558591, 2025). "However, the identification of a potentially POT1 PV in a family diagnosed with multiple early-onset melanomas underscores the need for continued genetic screening in hereditary melanoma cases, especially when CDKN2A, CDK4, and BAP1 aberrations are absent." (PMID 40851494, 2025). "CLL families with POT1 variants do not segregate with glioma or melanoma, suggesting that the penetrance of constitutional variants in POT1 or other genes involved in the shelterin complex is modest and act as moderate penetrance alleles." (PMID 40350252, 2025). "Four dermatopathologists reviewed the histology of melanomas from individuals with germline variants in POT1 (n = 30 melanomas, 17 individuals), TERF2IP (n = 4 melanomas, 3 individuals), ACD (n = 4 melanomas, 2 individuals), and TERT (n = 2 melanomas, 2 individuals)." (PMID 36876055, 2023). "Spitzoid subtype melanomas with complete spitzoid morphology (100% of tumor) and cutaneous melanomas with focal spitzoid morphology (≥25% of tumor) have also been observed in POT1 GPV carriers, suggesting dysfunctional telomere maintenance as a possible mechanism for spitzoid histology." (PMID 36876055, 2023). "The purpose of this study was to perform a mutational analysis of the seven candidate melanoma susceptibility genes (ACD, BAP1, MC1R, MITF, POT1, TERF2IP, and TERT) in high-risk melanoma patients (familial melanoma and MPM) from southeastern Brazil, besides the CDKN2A and CDK4 genes." (PMID 37958811, 2023). "The proband where the POT1 VUS was detected (MH16) also showed two MC1R variants (R/u), fair skin, light hair, a history of sunburn in childhood, a personal history of six primary melanomas and thyroid cancer, and a family history of melanoma." (PMID 37958811, 2023). "The mutations leading to POT1 inhibition, or mutations resulting in the loss of a binding site for TPP1, increase telomerase activity and are related to various malignancies, including melanoma." (PMID 35465855, 2022). "POT1, ACD, and TERF2IP are members of the Shelterin protein complex, crucial for the safeguard of telomeres, and have been also described to be mutated in familial melanoma patients." (PMID 34123788, 2021). "Less common melanoma susceptibly genes include CDKN2A/ARF, CDK4 (cyclin-dependent kinase 4), TERT, MITF (melanocyte inducing transcription factor), BAP1 (BRCA1 associated protein-1), and POT1 (protection of telomeres 1)." (PMID 34440462, 2021). "In the present study, a cohort of patients SPMs (n = 20) and MPMs (n = 19), sex-matched, was analyzed with our custom NGS panel that included 32 genes involved in melanoma susceptibility (e.g., CDKN2A, BAP1, POT1) and skin/hair pigmentation (e.g., TYR, TYRP1, OCA2)." (PMID 33748184, 2020). "As mutations in high-susceptibility genes greatly increase risk of melanoma development, individuals carrying CDKN2A, CDK4, BAP1, POT1, or MITF mutations should be educated on the importance of melanoma prevention and early detection and should undergo regular medical skin examination." (PMID 31717496, 2019).
melanoma (continued). "The detection of germline variants in genes involved in telomere regulation, such as RTEL1, POT1, TERC, and also in the telomerase reverse transcriptase promoter (TERT), has been used to identify increased risk of glioma and melanoma, as well as lung, bladder and pancreas cancer." (PMID 30305723, 2019). "That predicted telomere score has been established as a strong risk factor for melanoma in the general population, and germline POT1, TERT and other shelterin complex gene mutations have been found in melanoma families, suggests that telomere function is critical in melanoma susceptibility." (PMID 26433962, 2016). "Although the real role of POT1 in melanoma – as for TERT – needs to be fully understood, all these findings suggest that genes involved in telomere maintenance may contribute to the disease pathogenesis." (PMID 26322273, 2015). "Point mutations in POT1, particularly those affecting its oligonucleotide/oligosaccharide-binding (OB) fold domain (POT1 c.1432G > T (p.Cys476Phe) and c.1166C > T (p.Ala389Val), have been found in malignancies including chronic lymphocytic leukaemia (CLL), melanoma, and gliomas." (PMID 39578854, 2024). "Interestingly, the sole patient found to be a “double carrier” of the POT1 and MITF variants had an extremely high recurrence rate of melanoma (reporting 10 different resections over the years), possibly reflecting an additive/synergistic effect of the two variants." (PMID 38540414, 2024). "In the current study, all melanomas exhibiting spitzoid morphology from POT1 carriers occurred in adulthood (range: 35-77 years), although spitzoid subtype melanomas with complete spitzoid morphology (100% of tumor) have been reported in POT1 carriers as young as age 16 years." (PMID 36876055, 2023). "Even though POT1 seems to be the second major melanoma susceptibility gene, with 2%–4% of CDKN2A/CDK4-WT families carrying a pathogenic coding variant in this gene, its contribution to melanoma risk burden in the general population is minor, with ~0.5% of cases carrying pathogenic variants." (PMID 36539277, 2023). "As none of the variants described were found in melanoma cases, further studies might reveal that POT1 variants are specific to specific cancer types." (PMID 29523635, 2018). "Other high-risk melanoma genes have been discovered: cyclin-dependent kinase 4 (CDK4), BRCA-1 associated protein (BAP1), and recently via exome sequencing of dense melanoma families, several new high-risk genes affecting telomere functions have been identified: POT1, ACD, TERF2IP and TERT." (PMID 25803691, 2015). "Recently, germline variants in genes involved in telomere regulation, including POT1, TERT, ACD, and TERF2IP, have been identified in melanoma-prone families." (PMID 40851494, 2025). "Our study findings support the inclusion of TMG (POT1, TERF2IP, ACD, and TERT) on genetic testing panels when a familial melanoma case exhibits spitzoid morphology in at least 25% of the tumor cells." (PMID 36876055, 2023). "As estimates have suggested that POT1 may be the second major high-penetrance melanoma susceptibility gene after CDKN2A, being causal of disease predisposition in 2%–4% of CDKN2A/CDK4-negative families, 14 it has been included in multiple panels for genetic testing of melanoma families." (PMID 36539277, 2023). "POT1 alterations occur in < 10% of sporadic CLL, but also in familial malignancies, including CLL, melanoma, Hodgkin lymphoma, colorectal carcinoma, and angiosarcoma." (PMID 35456397, 2022). "A higher prevalence of germline mutations in BAP1 (not identified in our patients) and POT1 was also reported in a recent study by Pastorino and colleagues who identified seven carriers (2.6%) of mutations in each of these two genes among 273 Italian melanoma patients." (PMID 33050356, 2020). "Our study reveals that POT1 aberrations are not a major contributor to hereditary melanoma in Sweden." (PMID 40851494, 2025).
melanoma (continued). "The sample only included 308 melanoma cases with the great majority of tests carried out for breast cancer (n=6313), which had a negative correlation with POT1 (OR=0.71, 95% CI 0.53 to 0.945; p=0.019)." (PMID 40350252, 2025). "Furthermore, 13% (4 of 30) of melanomas from POT1 carriers and 50% (1 of 2) from TERT carriers were completely spitzoid, and therefore, were classified as spitzoid subtype melanomas." (PMID 36876055, 2023). "Therefore, panel testing for POT1, TERF2IP, ACD, and TERT should be considered when familial melanoma cases exhibit spitzoid differentiation." (PMID 36876055, 2023). "In a Spanish study of melanoma-prone families without CDKN2A or CDK4 mutations, four pedigrees (1.7%, n = 4/228) were identified with further distinct POT1 variants (p.Ile78Thr, p.Glu344*, c.255G > A and p.Asp598Serfs*22)." (PMID 32987645, 2020). "In particular, the protection of telomeres 1 (POT1) gene, adrenocortical dysplasia homolog (ACD) gene and telomeric repeat binding factor 2 interacting protein (TERF2IP) genes have been shown to be important in some melanoma families." (PMID 28097802, 2017). "Interestingly, one FDR of a carrier, who tested negative for the POT1 PV, was diagnosed with an invasive melanoma in the third decade of life." (PMID 40851494, 2025). "Compared to noncarriers (n = 139 melanomas), POT1 carriers (OR = 225.1, 95% confidence interval: 51.7-980.5; P < .001) and individuals with TERF2IP, ACD, and TERT variants (OR = 82.4, 95% confidence interval: 21.3-494.6; P < .001) had increased odds of spitzoid morphology." (PMID 36876055, 2023). "Furthermore, in Dutch melanoma-prone pedigrees (n = 451), two missense variants in the shelterin subunits ACD and TERF2IP were identified, but none in the POT1 gene." (PMID 32987645, 2020). "Small numbers preclude a statistical analysis of the numbers of naevi and atypical naevi in POT1 and TERT mutation carriers but the POT1 mutation carriers have a number of atypical naevi in the top 10 % of atypical naevi among our cohort of melanoma cases (data not shown)." (PMID 26433962, 2016). "In a single melanoma patient with a negative family cancer history, we identified a mutation in the ACD gene truncating the C-terminal proportion of the protein containing POT1- and TINF2-interacting domains required for the localization of ACD protein into the shelterin complex." (PMID 33050356, 2020).